ENSG00000289426 (novel transcript, antisense to ANKRD45)
Gene: Long non-coding RNA gene on chromosome 1 (173,637,693 to 173,703,596, forward strand). Ensembl gene ENSG00000289426.
Gene Ontology:
Biological process: RNA processing
Cellular component: nucleolus